Y_RNA (Y RNA )
Gene: Miscellaneous RNA gene on chromosome 4 (48,153,434 to 48,153,535, forward strand). Ensembl gene ENSG00000202014.
Homologues: Orthologues: chimpanzee Y_RNA (99% identical), guinea pig Y_RNA (88% identical). Paralogues in human: RNY3 (88% identical), Y_RNA (88% identical), Y_RNA (87% identical), Y_RNA (86% identical), RNY3P1 (85% identical), Y_RNA (85% identical), Y_RNA (84% identical), Y_RNA (83% identical), Y_RNA (82% identical), RNY3P11 (81% identical), RNY3P9 (81% identical), Y_RNA (81% identical), and 96 more.